TMEFF2 (transmembrane protein with EGF like and two follistatin like domains 2)
Description:
May be a survival factor for hippocampal and mesencephalic neurons. The shedded form up-regulates cancer cell proliferation, probably by promoting ERK1/2 phosphorylation.
Synonyms: TR-2; HPP1; TENB2; TPEF; TR; CT120.2
Tractability: Antibody: UniProt places it where antibodies can reach, with medium confidence; UniProt predicts a signal peptide or a membrane-spanning region; its Gene Ontology location is reachable by antibodies, with medium confidence. PROTAC: its protein half-life has been measured.
Gene: Protein-coding gene on chromosome 2 (191,949,043 to 192,194,985, reverse strand). Ensembl gene ENSG00000144339.
Subcellular location: Membrane (Isoform 1); Membrane (Isoform 2); Secreted (Isoform 3)
Gene Ontology:
Molecular function: protein binding
Biological process: negative regulation of cell migration; negative regulation of integrin biosynthetic process; negative regulation of stress fiber assembly; wound healing, spreading of cells; cell differentiation; response to stress
Cellular component: extracellular region; membrane
Genetic constraint (gnomAD): Loss-of-function variants: 21 observed, 44.26 expected, observed/expected ratio (o/e) 0.47, 90% interval 0.34 to 0.68. The upper end of that interval is the gene's LOEUF score, 0.68, which puts it in group 2 of 6, group 1 being the genes least tolerant of losing a copy. Missense variants: 308 observed, 417.78 expected, observed/expected ratio (o/e) 0.74, 90% interval 0.67 to 0.81. Synonymous variants: 148 observed, 155.7 expected, observed/expected ratio (o/e) 0.95, 90% interval 0.83 to 1.09.
Homologues: Orthologues: chimpanzee TMEFF2 (100% identical), macaque TMEFF2 (100% identical), pig TMEFF2 (99% identical), rabbit TMEFF2 (99% identical), rat Tmeff2 (99% identical), mouse Tmeff2 (99% identical), dog TMEFF2 (96% identical), guinea pig TMEFF2 (96% identical), tropical clawed frog tmeff2 (71% identical), zebrafish tmeff2a (67% identical), zebrafish tmeff2b (59% identical). Paralogues in human: TMEFF1 (49% identical), LAMA1 (24% identical), LAMA3 (24% identical), LAMA2 (23% identical), LAMA5 (23% identical), LAMB1 (23% identical), LAMB2 (23% identical), LAMB4 (22% identical), LAMC1 (21% identical), USH2A (21% identical), LAMC3 (20% identical), HSPG2 (20% identical), and 15 more.
Diseases named in the same sentence as TMEFF2 in open-access papers:
TMEFF2 is named in the same sentence as 45 diseases in open-access papers, as found by Europe PMC text mining. Sharing a sentence is not in itself a finding about the gene and the disease. The quoted sentences say what the papers report.
prostate carcinoma (23 papers, 2007 to 2025). A carcinoma that arises from epithelial cells of the prostate gland. "As evidence for its positive role in cell proliferation,elevated TMEFF2 expression has been associated with higher prostate cancer grade andhormone independence by several groups." (PMID 21559523, 2011). "The biological function of AC098617.1 is currently unknown; however, its associated gene, TMEFF2, is recognized as an androgen-regulated tumor suppressor in prostate cancer." (PMID 40004558, 2025). "Moreover, we have identified that TMEFF2 is also a novel substrate for other proteases implicated in prostate cancer, including two ADAMs (ADAM9 and ADAM12) and the type II transmembrane serine proteinases (TTSPs) matriptase‐1 and hepsin." (PMID 28762604, 2018). "LE-2 cells specifically expressed TMEFF2 (Fig 2B6), which is an androgen-dependent suppressor of prostate cancer cell growth." (PMID 41468516, 2025). "A previous study found that TMEFF2 is a critical factor in modulating one‐carbon metabolism and the invasion of prostate cancer cells." (PMID 39980308, 2025). "Further efforts are necessary to better characterize the role and regulation of TMEFF2 in normal tissues and prostate cancer and identify the best model systems to allow translation of preclinical efficacy to patient benefit." (PMID 39832129, 2025). "TMEFF2 is downregulated by promoter hypermethylation in several neoplastic diseases, such as colon cancer, oesophageal cancer, gastric cancer, and prostate cancer." (PMID 33663520, 2021). "Vera Knauper’s group actively searched for answers to the discrepancies between the oncogenic versus onco-suppressive roles of TMEFF2 in prostate cancer." (PMID 33371267, 2020). "It is indeed intriguing to notice numerous prostate cancer studies reporting opposing data regarding the relation of TMEFF2 to androgens and its onco-suppressive versus potentially oncogenic role." (PMID 33371267, 2020). "Numerous studies regarding the role of TMEFF2 in prostate cancer revolve around its progression from the androgen-dependent to androgen-independent stages." (PMID 33371267, 2020). "ADAM17, the most notable protease responsible for TMEFF2 ectodomain shedding (discussed in detail in the following section—TMEFF2 in prostate cancer), also acts as the α-secretase for AβPP and cleaves it into a secreted form." (PMID 33371267, 2020). "In the 22Rv1 prostate cancer cell line, the TMEFF2 puncta can be observed mainly along the rim of the nuclei (through immunofluorescence) and TMEFF2 has also been reported to colocalise with β-actin and α-tubulin in these cells." (PMID 33371267, 2020). "The conflicting oncogenic versus onco-suppressive role of TMEFF2 in prostate cancer literature is more complex to untangle." (PMID 33371267, 2020). "Despite undergoing extensive investigation over the last two decades, the primary literature regarding TMEFF2 is incoherent and offers conflicting information, in particular, the oncogenic vs. onco-suppressive role of TMEFF2 in prostate cancer." (PMID 33371267, 2020). "Lastly, in 2006, Quayle and Sadar reported a short isoform of TMEFF2 (TMEFF2-S) in the LNCaP prostate cancer cell line." (PMID 33371267, 2020). "TMEFF2 is a previously identified AR-target gene, which has been shown to exhibit anti-proliferative effects in prostate cancer cells." (PMID 27036029, 2016). "Conversely, other reports showed that a significant proportion of prostate carcinomas exhibit TMEFF2 overexpression and in vivo studies using LNCaP xenografts show that TMEFF2 inhibition results in tumor growth arrest, favoring its role as an oncogene." (PMID 25595908, 2015). "Changes in the expression of TMEFF2 protein have been documented in prostate cancer, and a potential role for TMEFF2 in this disease has been proposed." (PMID 23405127, 2013). "A role for TMEFF2 in prostate cancer was suggested by studies indicating that TMEFF2 expression is altered in a significant fraction of primary and metastatic prostate tumors." (PMID 23405127, 2013).
prostate carcinoma (continued). "Expression of TMEFF2 is deregulated in prostate cancer, suggesting a role in this disease, but the molecular mechanism(s) involved in this effect are not clear." (PMID 23405127, 2013). "DHT-induced expression of endogenous TMEFF2 was also observed in the androgen-responsive prostate cancer LNCaP cells." (PMID 23405127, 2013). "In contrast, others havereported down-regulation of TMEFF2 in androgen-independent prostate cancerxenografts, as well as growth inhibition induced by ectopic expression of TMEFF2 inandrogen-independent prostate cancer cell lines." (PMID 21559523, 2011). "In contrast, the meanTMEFF2 mRNA expression is elevated in prostate cancer tissues, especiallynon-metastatic prostate cancer tissues, compared to normal prostates, suggesting apossible tissue and cell context-dependent dual function of TMEFF2 in humancancers." (PMID 21559523, 2011). "The clinical activity observed in this first-in-human study indicates that TMEFF2 may be a potential therapeutic target for prostate cancer." (PMID 39832129, 2025). "However, the role of TMEFF2 in prostate cancer is controversial, and several studies have shown opposite functions, oncogenic and tumor-suppressive, for this transmembrane protein." (PMID 35565454, 2022). "It was demonstrated that histone deacetylases as well as c-Myc, STAT1 and STAT3 may contribute independently to the transcriptional suppression of TMEFF2 in colon cancer, prostate cancer and gastric cancer." (PMID 33663520, 2021). "However, in prostate cancer, the extracellular domain of TMEFF2 is shed from the cell membrane and promotes cell proliferation by combining with the ErbB1 receptor." (PMID 33663520, 2021). "In addition, they also reported that TMEFF2 expression was markedly increased in prostate carcinoma vs. benign prostate hyperplasia and that its mRNA levels increased in higher-grade prostate cancers." (PMID 33371267, 2020). "Moreover, reduced TMEFF2 mRNA levels were observed in the androgen-independent prostate cancer xenograft models (LAPC9-AI, LAPC3-AI and LAPC4-AI) when compared to their androgen-dependent counterparts." (PMID 33371267, 2020). "In conclusion, for these authors, TMEFF2 is an androgen-regulated gene and its expression was abolished upon cessation of androgens, but it reappeared with even higher intensity in androgen-independent recurrent prostate cancer." (PMID 33371267, 2020). "Importantly, when TMEFF2 was ectopically expressed in DU145 and PC3 cells, it impaired their proliferation significantly; although TMEFF2 was upregulated by androgens, it exhibited antiproliferative effects in prostate cancer." (PMID 33371267, 2020). "To investigate the role of the uORFs in regulating TMEFF2 protein expression, we asked whether blocking translation of the uORFs would affect translation of the TMEFF2 protein in human prostate cancer cell lines." (PMID 23405127, 2013). "Therefore, the interaction of TMEFF2 with SARDH further suggests a role for TMEFF2 in prostate cancer progression." (PMID 23405127, 2013). "The present study reveals a novel role for androgens in the regulation of TMEFF2 translation that could account for the changes in TMEFF2 expression observed in prostate cancer." (PMID 23405127, 2013). "TMEFF2 is also currently being investigated as a target for antibody-based therapy in the treatment of prostate cancer, confirming that our approach identified novel transcripts which may be of interest in the study of prostate cancer." (PMID 17257419, 2007). "TMEFF2 codifies an androgen-regulated transmembrane protein, normally restricted to the brain and prostate tissues, initially described as a tumor suppressor gene for its inhibition of cell growth and hypermethylated status in several tumors, including prostate carcinomas." (PMID 25595908, 2015). "Therefore, TMEFF2 upregulation in response to AR signaling may initially serve as a barrier for malignant progression of prostate cancer." (PMID 23405127, 2013).
prostate carcinoma (continued). "They reported TMEFF2 expression to be exclusive in LNCaP and CWR22 prostate cancer cell lines in addition to the glioblastoma cell lines U118 and U187MG." (PMID 33371267, 2020). "TMEFF2 and SARDH cooperate to modulate one-carbon metabolism and the invasion of prostate cancer cells." (PMID 31552180, 2019). "TMEFF2 has also been identified in human testes, shown to prevent PDGF-AA-induced cellular proliferation, to be upregulated by androgen in some prostate cancer cells, and to have oncogenic and onco-suppressive actions depending on the tissue/cancer type context." (PMID 36674726, 2023). "Moreover, we downloaded the GEO data and found that TMEFF2 was highly expressed only in localized prostate cancer tissue and not in CRPC tissue." (PMID 38575966, 2024). "In most studies, TMEFF2 has been found to suppress growth, whereas Nazim Ali and Vera Knauper proposed that shedding of the soluble TMEFF2 ectodomain would induce proliferation by inducing ERK1/2 phosphorylation in an ErbB1-dependent manner in prostate cancer cells." (PMID 33663520, 2021). "Moreover, ectopic overexpression of TMEFF2 had no detrimental effect whatsoever on the proliferation of prostate cancer cells in culture or in xenografts." (PMID 33371267, 2020). "However, the molecular mechanisms leading to deregulation of TMEFF2 expression in prostate cancer are not known." (PMID 23405127, 2013). "TMEFF2 is a type I transmembrane protein with two follistatin (FS) and one EGF‐like domain over‐expressed in prostate cancer; however its biological role in prostate cancer development and progression remains unclear, which may, at least in part, be explained by its proteolytic processing." (PMID 28762604, 2018). "However, the marked expression of TMEFF2 in androgen-dependent LNCap cells and its absence in the androgen-independent DU145 and PC3 prostate cancer cells as well as the absence of TMEFF2 expression in the primary culture of human normal prostatic epithelial (PrEC) cells remain intriguing." (PMID 33371267, 2020).
gastric cancer (6 papers, 2018 to 2022). A primary or metastatic malignant neoplasm involving the stomach. "The group established an inverse correlation between TMEFF2 expression and its promoter methylation along the progression stages of gastric cancer and an association between low TMEFF2 expression and poor survival." (PMID 33371267, 2020). "Our data are also consistent with previous reports that TMEFF2 expression is downregulated and negatively correlated with tumour histologic grade in gastric cancer and colon cancer." (PMID 33663520, 2021). "The investigators also proposed that TMEFF2 had a role in maintaining genomic integrity as TMEFF2 knockdown in GES-1 gastric cancer cells led to an increase in DNA damage." (PMID 33371267, 2020). "On the other hand, TMEFF2 overexpression decreased STAT3 phosphorylation in AGS gastric cancer cells both in culture and in xenografts (TMEFF2 overexpression also resulted in a dramatic decrease in the tumour size)." (PMID 33371267, 2020). "In a later study, the same research group investigated the role of TMEFF2 in Helicobacter pylori-induced gastric cancer development using cell cultures, mouse models and human gastric tissue pathology." (PMID 33371267, 2020). "Higher co-expression of TMEFF2 and SHP-1 is closely associated with favorable outcomes in gastric cancer patients." (PMID 29409467, 2018). "It has been found that LINC-DUBR could upregulate TMEFF2 expression to inhibit the proliferation of gastric cancer cells by targeting miR-641." (PMID 35281523, 2022). "In gastric cancer, TMEFF2 deregulation may play an important role in the progression of gastric carcinogenesis." (PMID 33663520, 2021). "These authors concluded that TMEFF2 could act as a tumor suppressor in gastric cancer through direct interaction with SHP-1 via its intercellular domain." (PMID 30202514, 2018). "Moreover, no mutations were found in the TMEFF2 intracellular domain in gastric cancer patients (TGCA data)." (PMID 33371267, 2020). "Moreover, TMEFF2 methylation increases with breast, colon and gastric cancer progression." (PMID 33371267, 2020). "They observed that the levels of this vitamin were correlated with the mRNA expression of the transmembrane protein with epidermal growth factor- (EGF-) like and two follistatin-like domains 2 (TMEFF2) in gastric cancer (GC) patients." (PMID 31934267, 2019). "The interaction of TMEFF2 with SHP1 in AGS and MKN45 gastric cancer cells resulted in cell cycle arrest, induction of apoptosis and a decrease in cell proliferation both in vitro and in vivo (xenograft models)." (PMID 33371267, 2020).
pancreatic carcinoma (6 papers, 2018 to 2026). "CONCLUSION: MiR-641 acts as an oncogene that promotes pancreatic cancer cell growth, invasion as well as stem-cell-like features, which is realized by regulating the expression of TMEFF2." (PMID 41653388, 2026). "MiR-641 targeted TMEFF2/MEK/PI3K for promoting pancreatic cancer cells’ stem-cell-like characteristics." (PMID 41653388, 2026). "A recent study found over-expression of LINC01963 in pancreatic carcinoma cells inhibited proliferation of pancretic cells via the miR-641/TMEFF2 pathway." (PMID 33767582, 2021). "On the other hand, when compared to adjacent normal tissue, TMEFF2 mRNA was downregulated in pancreatic cancer (72 patients), and an inverse correlation was observed between TEMFF2 protein in pancreatic cancer tissue and the clinical stage of the disease." (PMID 33371267, 2020). "LncRNA LINC01963 represses pancreatic carcinoma progression via regulating miR-641/TMEFF2 axis." (PMID 38006396, 2023). "The lncRNA LINC01963 has been confirmed to be significantly lower in pancreatic carcinoma tissues and cell lines by targeting miR-641/TMEFF2, whereas silence of LINC01963 could improve the development of cell culture tumors." (PMID 35538487, 2022). "The study also reported that TMEFF2 overexpression in AsPC1 and Panc1 pancreatic cancer cells (i) impairs cell proliferation both in vitro and in vivo (xenograft), (ii) decreases their invasion and migration capacities, and (iii) downregulates EMT signature proteins." (PMID 33371267, 2020).